DNMT3B (DNA methyltransferase 3 beta)
Diseases named in the same sentence as DNMT3B in open-access papers (continued):
Sharing a sentence is not in itself a finding about the gene and the disease.
tumor (continued). "According to public databases, our data strongly suggest CDK6, DNMT3A and DNMT3B as direct targets of miR-29a-3p: disallowed tumor-suppressive function of this miRNA may stimulate tumorigenesis by promoting cell cycle progression and altering de novo methylation of the genome." (PMID 27829219, 2016). "Therefore, DNMT3b may act as a tumor suppressor or an oncogene depending on tumor stage or on the type of tumor cell population." (PMID 26556862, 2016). "Importantly, enforced abundant nuclear accumulation of FOXO3a could decrease expression of DNMT3B with synergistic inhibition of tumor growth and decrease in methylation status on TSGs in human lung tumor xenograft specimens." (PMID 25949795, 2014). "Evidence shows that piperine modulates DNA methylation (↓ DNMT3B), histone acetylation (↓ HDAC activity), and microRNA networks (↑ miR-29c, ↓ miR-383), thereby reshaping key oncogenic and tumor-suppressive pathways." (PMID 42278671, 2026). "In this study, we investigated the clinical and molecular significance of piR-823 in OC and explored its potential regulatory role in tumor progression through a proposed epigenetic axis involving PIWIL1, DNMT3B, and CDH1." (PMID 41596471, 2026). "In each cohort, the DNMT3B− and DNMT3B+ groups were defined using a threshold corresponding to the median expression level of DNMT3B in all tumour samples." (PMID 40585280, 2025). "The results showed that IL2RA, DNMT3B, ADRM1, and NRIP1 were highly expressed in tumor tissue compared to normal tissue, while ALDH2, NYNRIN, LSP1, and CALCRL were the opposite." (PMID 38322112, 2024). "The expression levels of three writers (DNMT1, DNMT3A, DNMT3B), two erasers (TET1, TET3), and eight readers (MBD4, ZBTB33, UHRF1, UHRF2, UNG, TDG, NTHL1, SMUG1) were dramatically higher in tumor tissues (p < 0.05)." (PMID 38317133, 2024). "This pathway starts from CD28 expressed on tumor plasma cells and, through the PI3K-miR29b-DNMT3B axis, leads to epigenetic silencing of immunoproteasome subunits, allowing MM plasma cells to elude immunosurveillance." (PMID 38654298, 2024). "In addition, others have hypothesized a similar carcinogenesis model in which DNMT3A and DNMT3B are specifically recruited during tumor initiation and promotion, with a subsequent downregulation of their expression, whereas DNMT1 is involved in tumor progression." (PMID 37894317, 2023). "This approach effectively suppressed the mRNA expression of CDK6, DNMT3B, and MCL1 in the tumor tissue by approximately 57.4%, 40.5%, and 52.4% respectively." (PMID 37705098, 2023). "The miR-29 family was reported to function as tumor suppressor microRNA through sponging DNMT3A and DNMT3B." (PMID 36870998, 2023). "The effect of TQ, PIP, and SOR treatment on the expression of DNMT3B/HDAC3 genes and the tumor suppressor miRNA-29c was examined by RT- PCR." (PMID 36870998, 2023). "Their research revealed that miR-149 exhibited low expression levels, while DNMT3B and ring finger protein 2 (RNF2) displayed high expression levels within ESCC tumor samples." (PMID 37705098, 2023). "Recent evidence has shown that tumor invasion into neighboring tissue is regulated by various methyltransferases, such as DNMT1 and DNMT3B." (PMID 37367043, 2023). "miR-149 was poorly expressed whereas DNA methyltransferase 3 beta (DNMT3B) and ring finger protein 2 (RNF2) were abundantly expressed in ESCC tumor samples." (PMID 35129056, 2022). "The mRNA levels of DNA methyltransferases (including DNMT1, DNMT3A, and DNMT3B) were significantly higher in KIRC patients and correlated with tumor stage and histologic tumor grade than in normal." (PMID 36186442, 2022). "Several DNA5mC regulators were found to be significantly overexpressed in tumor tissues, including DNMT1, DNMT3B, TET2, TET3, MBD1, and SMUG1." (PMID 36425533, 2022).
tumor (continued). "An analysis of the mean z-score in each data set revealed that DNMT3A, DNMT3B, and HDAC1/2/3 tended to have positively shifted z-scores indicating an increase in mean gene expression in the tumor populations." (PMID 36050516, 2022). "Immunohistochemistry analysis showed that the expression of WTAP, DNMT1, and DNMT3B in tumor tissues was significantly higher than that in paracancerous tissues, whereas the expression of TRMT6 was low in tumor tissues." (PMID 36203569, 2022). "For instance, overexpression of miR-29c-3p in HCC can activate large tumor suppressor gene 1 (LATS1) expression and demethylation of LATS1 via DNMT3B, thereby impeding HCC cell tumor growth and migration both in vitro and in vivo." (PMID 36246623, 2022). "In summary, our findings show that the combined application of GSK126 and 5-Aza synergistically inhibited EZH2 and DNMT3B to derepress the expression of TCF3, and profoundly blocked EC tumor progression in mouse models." (PMID 34175897, 2021). "Studies on tumor growth have demonstrated the great potential of E2 in the induction of changes involving DNMT1, DNMT3A, and DNMT3B related to DNA methylation." (PMID 33915762, 2021). "Curcumin was shown to induce DNA hypomethylation in several different human tumor cell lines by inhibiting the activities of DNMT1 and DNMT3B." (PMID 32878338, 2020). "The results above indicated that the DNMT3B-induced downregulation of HOXB13 mediates methylation and regulates C-myc expression via β-catenin/TCF4 signaling, enhancing tumor progression and resulting in a poor prognosis." (PMID 31815008, 2019). "Kaplan-Meier analysis of our patients showed that DNMT3b and OCT4 gene expression levels were positively correlated with tumor recurrence." (PMID 31771617, 2019). "Taken together, these results strongly suggest that the levels of IL-6, DNMT3b/1, and OCT4 are highly correlated and that they play a role in early tumor recurrence and poor prognosis of HCC patients." (PMID 31771617, 2019). "In contrast, constitutively high MYC levels in tumor cells drive the expression of DNMT1 and DNMT3B." (PMID 29100357, 2017). "In AML, microRNA-29b targets DNMT3A and DNMT3B directly and DNMT1 indirectly thereby inducing global DNA hypomethylation and tumor suppressor gene expression." (PMID 29100357, 2017). "RT-qPCR and Western blot analysis of tumor cells derived from EμSRα-tTA;tet-o-MYC transgenic mice indicate that DNMT3B expression levels were elevated in MYC-driven T-ALL compared to normal spleen from wild-type C57BL/6J mice." (PMID 29100357, 2017). "Our study shows, for the first time, an aberrant expression of DNMT3B gene in both ARMS and ERMS primary tumours and cell lines." (PMID 27764816, 2016). "Here we demonstrate in several tumor cell lines an interaction between KDM1A and both DNMT1 and DNMT3B." (PMID 27449289, 2016). "Relatively higher expression of DNA methyl-transferases (DNMT1 and DNMT3b) and HIF-1α genes (34-50%, P<0.05) were also detected in tumor tissues." (PMID 25938433, 2015). "We also compared values from mammary gland and tumor in each experimental group finding, in general, a decrease of DNMT expression in tumor, mainly in DNMT3a and DNMT3b." (PMID 26401660, 2015). "Recently, more reports have shown that miR-29 family regulated tumorigenesis and tumor progression by targeting DNMT3A, DNMT3B, TIAM1, cyclin E, MMP2, ID1, SPARC and COL3A1." (PMID 23936390, 2013). "In vitro studies using non-colonic cell lines have indicated that miR-148a exerts a tumor suppressive function by targeting several genes such as PXR, TGIF2, MSX1, CDC25B, DNMT1 and DNMT3b." (PMID 23056401, 2012). "In tumor tissue as compared to normal brain, DNMT1 andDNMT3b were significantly upregulated (DNMT1: 2.5-fold, DNMT3b: 3.2-fold, p<0.001); thedegree of upregulation did not correlate with MGMT promotermethylation status and MGMT mRNA expression." (PMID 21365007, 2011).
tumor (continued). "Abnormal DNA methylation is thought to be a major early event in the development of tumours where DNA methyltransferases (DNMTs), DNMT1, DNMT3A and DNMT3B have been identified as DNA methylation functional enzymes in eukaryotic cells." (PMID 20128888, 2010). "Increased expression of DNMT3A and DNMT3B as de novo DNA methyltransferase are common in many tumours which implies the that aberrant DNMT3A and DNMT3B expression are involved in carcinogenesis." (PMID 20128888, 2010). "In this study, we measured the mRNA expression level of three methylation-related genes (DNMT1, DNMT3b and MBD2) in NSCLC tumour tissues using quantitative real-time PCR and evaluated their prognostic values." (PMID 18414412, 2008). "As in the initial tumor series, BRCA2, DNMT3B and CCNE1 mRNA levels were significantly higher in patients who relapsed than in those who did not relapse." (PMID 15606925, 2004). "Expression of DNMT3B, PIWIL1, NANOG, OCT4, and CDH2 was significantly elevated in tumor samples compared to normal controls (p = 8.33 × 10−45, 1.01 × 10−23, 7.76 × 10−6, 3.22 × 10−54, and 1.82 × 10−22, respectively), indicating strong tumor-specific upregulation of these genes." (PMID 41596471, 2026). "Both simple and multiple linear regression analyses indicated that piR-823 and DNMT3B have a positive regulatory effect on stemness markers (OCT4 and NANOG), while DNMT3B mainly governed EMT-related marker (CDH2) expression, further supporting their involvement in tumor progression and metastasis." (PMID 41596471, 2026). "Histological analyses from knockout mice indicated that the loss of Dnmt3a triggers tumorigenesis through the upregulation of the adipogenesis regulator PPARγ, while the absence of Dnmt3b facilitates tumour growth and metastasis." (PMID 39846570, 2025). "Furthermore, these enzymes are considered tumor suppressors in certain tissues and oncogenes in others, while DNMT3A and DNMT3B have occasionally opposite effects." (PMID 39819598, 2025). "DNMT3B is significantly overexpressed in tumor tissues compared to that in adjacent nontumor tissues." (PMID 39108206, 2024). "Specifically, S-nitrosylation of DNMT3B reduces its enzymatic activity, leading to an abnormal upregulation of the Cyclin D2 gene (CCND2), which is necessary for the proliferation of certain tumor cells." (PMID 39185313, 2024). "Namely, we hypothesize that DNMT1 and DNTM3A seem to play a role in tumor initiation, DNMT3B in tumor progression and DNMT3L in tumor relapse, whereas DNMT2 may have an opposite role." (PMID 37894317, 2023). "For example, DNMT1, DNMT3A, and DNMT3B have been shown to promote LAML, which may be due to DNMTs silencing certain tumor suppressor genes through hypermethylation of these genes, thereby promoting the progression of LAML." (PMID 37308972, 2023). "In addition, the IHC staining of xenograft tumor tissue demonstrated that the protein levels of DNMT1 and DNMT3B were significantly decreased after ZVI@CMC treatment." (PMID 36310172, 2022). "In conclusion, our study suggested that miR-29b-3p could influence DNA damage response by regulating the expression of DNMT3B, Bcl-2, PI3KR1, AKT2, and RBL1, thereby affecting tumor radioresistance." (PMID 34604239, 2021). "Although the exact mechanism remains unclear, evidence suggests that the hypermethylation regulated interaction between DNMT3B and MYH11 may contribute to the tumor progression." (PMID 35096593, 2021). "Intriguingly, studies on tumor growth have revealed the great potential of E2 in the induction of changes related to DNA methylation involving DNA methyltransferases (DNMT1, DNMT3A, and DNMT3B)." (PMID 33915762, 2021). "In the epigenetic regulation, E7 could upregulate DNA methyltransferases DNMT1, DNMT3A, and DNMT3B to promote genomic instability 17, induce methylation of CXCL14 to promote tumor growth via angiogenesis." (PMID 34729114, 2021).
tumor (continued). "Here we show that decreasing Dnmt3b’s activities in vivo in Dnmt3b+/−, Dnmt3b+/CI, and Dnmt3bCI/CI mice results in development of various hematologic malignancies, mostly TCL and CLL, highlighting its tumor suppressor function in spontaneous lymphomagenesis." (PMID 33450231, 2021). "Our current study demonstrated that the mRNA levels in cells and the protein levels in the supernatants of DNMT1, DNMT3a, DNMT3b, and HDAC1 increased with the increase of cell malignancy, which has provided a critical evidence in the search for tumor biomarkers from body fluid." (PMID 33383878, 2020). "On the contrary, Eads and his colleagues found DNMTs, including DNMT3B, were increased or not in tumours when RNA levels had normalized using different housekeeping gene controls." (PMID 33061956, 2020). "DNMT3B expression was not correlated with gender (P >0.9999), age (P = 0.6821), or tumor size (P=0.7055), but was correlated with tumor (T) stages (P=0.0187), node metastasis (P =0.0235), and the muscle-invasive stage (P =0.0449)." (PMID 33221743, 2020). "Besides, in hormone refractory prostate cancers, the tumor cells presented drug resistance and increased the expressions of DNMT1 and DNMT3b." (PMID 31771617, 2019). "Our findings highlight the anti-tumor ability of HOTAIR silencing in AML, suggesting that silencing HOTAIR was able to inhibit AML progression through HOXA5 promoter demethylation by decreasing Dnmt3b." (PMID 31168296, 2019). "Furthermore, we recently reported that MYC deregulates the expression of methylation modifiers, DNMT3B and DNMT1, essential for tumor maintenance." (PMID 31266538, 2019). "Concordantly, we found a positive correlation between the fold change in expression of DNMT3B and nc886 promoter methylation in matched normal to tumor tissue in the TCGA-PRAD cohort, which favors DNMT3B involvement in nc886 promoter methylation during neoplastic transformation in the prostate." (PMID 29394925, 2018). "VEGFA induced DNMT3A, but not related DNMT3B or DNMT1, and DNMT3A knockdown prevented VEGFA‐mediated miR‐128 loss and the increases in Bmi1 expression and OVCA tumor sphere formation in vitro." (PMID 28179359, 2017). "While we did not observe any consistent changes in the levels of Dnmt1 in either tumor type, we did see down regulation of Dnmt3b in PTCL, but not CLL samples, relative to their respective controls." (PMID 27677595, 2016). "Preliminary results indicate that DNMT3B and MYC are able to interact in RD cells (Megiorni & Marampon, unpublished data), suggesting a possible molecular mechanism for site-specific DNA methylation/repression of target genes in ERMS tumours." (PMID 27764816, 2016). "Regarding the DNMTs, the writers of DNA methylation reactions, in this study only DNMT3A showed increased methylation levels in tumor tissue, comparable to those found in adjacent thymic tissue, with respect to blood; the other two DNMTs genes, DNMT1 and DNMT3B, resulted hypomethylated." (PMID 27999265, 2016). "DNMT3B and DNMT1 studied regions were largely hypomethylated both in blood and tumor tissue DNA." (PMID 27999265, 2016). "Although the expression of p18INK4C was partially affected by DNMT1, no significant upregulation of DNMT1 (P > 0.05) or DNMT3B (P > 0.05) mRNA levels was observed in 35 GC tissues (the same tissues used to detect DNMT3A expression) compared with non-tumor tissues." (PMID 26350239, 2015). "Hence, we investigated the effects of the high fat diets on DNMT function, determining mRNA levels of DNMT1, DNMT3a and DNMT3b, as well as DNMT activity in mammary gland and tumor at 246 days of age." (PMID 26401660, 2015). "In contrast, DNMT3a was decreased in the castrated mice (P < 0.05), and DNMT1 and DNMT3b were both significantly decreased in the combination group (P < 0.01 and P < 0.05, respectively), which was not consistent with the tumor sizes in the different groups." (PMID 24885368, 2014).
tumor (continued). "The IHC data of TMA slides confirmed this finding that DNMT3b was overexpressed in tumor tissues than the adjacent non-malignant epithelial tissues." (PMID 24625449, 2014). "Strikingly, gene expression and methylation profiling analyses revealed a common molecular signature enriched for primitive neural features, high LIN28/LIN28B and DNMT3B expression for all group 1 CNS-PNETs regardless of location or tumor histology." (PMID 24839957, 2014). "In PC patients, the univariate analysis showed a protective role, in terms of reduced mortality, of high DNMT3B expression levels in noninvasive tumours, whereas in invasive tumours such an effect for DNMT3B overexpression was not further observed." (PMID 22919364, 2012). "The exact nature of the defect in methylation machinery of tumour cells remain unclear; however, it may be related to the expression of DNA methyltransferases (DNMTs), primarily DNMT1, DNMT3a, and DNMT3b." (PMID 18414412, 2008). "DNMT3B is significantly overexpressed in tumour samples compared to nontumour breast tissues." (PMID 40585280, 2025). "DNMT3B expression was significantly higher in tumor cells than normal epithelial cell GES-1." (PMID 39185313, 2024). "DNMT3B was significantly overexpressed in tumor tissues compared to adjacent nontumor tissues." (PMID 39108206, 2024). "However, we showed that CHIR-99021 acts specifically on HSCs in the tumor environment and exerts anti-fibrotic effects by regulating DNMT3B activity rather than GSK3β activity." (PMID 38168140, 2024). "Considering the high expression of DNMT3A, TET1, DNMT3B, TET3, UHRF2, DNMT1, UHRF1and TDG in Subtype B, changing the tumor microenvironment cell infiltration characteristics by reversing expression of these DNA methylation regulators may be more clinically practical." (PMID 35771147, 2022). "Even though the status of neither DNMT3b nor HDAC9 has association with PD-L1 levels in our cohort, their inhibitors might upregulate expression of immunostimulatory signals in tumor cells." (PMID 35226658, 2022). "In addition, we found that AMG 706 treatment reduced tumor cell proliferation and migration abilities could be reversed by MrgprF knockdown, possibly via reducing DNMT3A and DNMT3B expression." (PMID 35504869, 2022). "Notably, DNMT3B expression correlated with increased tumor invasion and higher grade, but not with lymph node status." (PMID 34175897, 2021). "DNMT3B expression was not correlated with gender, age, or tumor size." (PMID 33221743, 2020). "Next, DNMT3B expression was positively correlated with tumor size, vascular invasion, and intrahepatic metastasis (p < 0.005), and LATS1 expression was positively correlated with tumor size, TNM (tumor, node, metastasis) stage, and intrahepatic metastasis (p < 0.005)." (PMID 30718452, 2019). "However, Dnmt3a has a critical role in suppressing carcinogen-induced squamous tumor initiation, but not progression, while both Dnmt3a and Dnmt3b concertedly prevent tumor progression." (PMID 28425913, 2017). "However, overexpression of methylating enzymes (DNMT1 and DNMT3B) enzymes was not a critical determinate of tumor-specific promoter hypermethylation of RASSF1A and FUS1, which revealed, respectively, high and moderate methylation frequency in our study." (PMID 26112163, 2015). "Finally, the five candidate genes DNMT3B, EXO1, MCM10, CENPF and CENPE were combined in a new prognosis tool, Gene Expression Classifier or GEC, that stratifies patients according to the number of activated genes in the corresponding tumour (activation status ON)." (PMID 37592220, 2023). "Our results showed that PHF14 expression was inversely associated with the level of SMAD7 in tumor specimens with high DNMT3B expression, and by contrast, the correlation between the expression levels of PHF14 and SMAD7 was not significant in those expressing low DNMT3B." (PMID 37072414, 2023).